TNFAIP3 (TNF alpha induced protein 3)
Diseases named in the same sentence as TNFAIP3 in open-access papers (continued):
Sharing a sentence is not in itself a finding about the gene and the disease.
atherosclerosis (10 papers, 2017 to 2025). A disease characterized by the build-up of fatty material and calcium deposition in the arterial wall resulting in partial or complete occlusion of the arterial lumen. "ICAM1, MAP3K8 and TNFAIP3 are highly associated with the development of atherosclerosis." (PMID 40607379, 2025). "Intersection of three datasets: our Ninj1-associated DEGs, atherosclerosis-related genes from GSE57691, and inflammation-associated genes from DisGeNET C0021368, yielded 11 overlapping genes including CXCL-8, TNFAIP3, and CXCL-1." (PMID 41280941, 2025). "IER3 is an NF-κB-responsive gene similar to TNFAIP3, which is also upregulated in atherosclerosis, inhibited endothelial neogenesis, and has an anti-myocardial hypertrophic function." (PMID 39234566, 2024). "Therefore, the involvement of hsa-miR-125b in inflammation during atherosclerosis can also be proposed via TNFAIP3." (PMID 35488341, 2022). "However IL-1α’s effect was still pro-atherogenic because TNFAIP3 is reported to decrease inflammation and atherosclerosis in murine models." (PMID 28323859, 2017). "Thus, the combination of previous and current research results revealed that TNF, CXCL8, SOCS3 and TNFAIP3 may be involved in chronic inflammatory lesions that eventually result in atherosclerosis, CAD or IS." (PMID 32164735, 2020). "In particular, CXCR4, ICAM-1, Tumor Necrosis Factor Alpha-Induced Protein 3 (TNFAIP3), and Caspase-8 (CASP8) genes that present a role in atherosclerosis development at different level and with different functions were considered." (PMID 30356351, 2018).
colorectal cancer (10 papers, 2015 to 2024). A primary or metastatic malignant neoplasm that affects the colon or rectum. "Colorectal cancer-derived integrin beta-like 1 (ITGBL1)-rich EVs stimulate the NF-κB signaling pathway via tumor necrosis factor (TNF) alpha-induced protein 3 (TNFAIP3) to activate fibroblasts at metastatic sites and promote cancer metastasis." (PMID 38318528, 2024). "The seven significant colorectal cancer associated genes shortlisted from the differentially expressed genes were CALD1, CTNNB1, CXCL14, PTCH1, CXCL8, TNFAIP3, and NNMT after mapping with PubMed, OMIM, MeSH, and PMC databases." (PMID 32523911, 2020). "Another prognostic biomarker of colorectal cancer is the TNFAIP3 which may also act as the tumor suppressor gene." (PMID 32523911, 2020). "Taken together, decreased expression of TNFAIP3 and its partners contribute to inflammation and up-regulation of apoptosis inhibitors that may create microenvironment for colorectal cancer." (PMID 28842689, 2017).
gastric cancer (10 papers, 2021 to 2025). A primary or metastatic malignant neoplasm involving the stomach. "Furthermore, TNFAIP3 was shown to promote gastric cancer cell proliferation, migration, and invasion by stabilizing Snail and ZEB1 proteins." (PMID 40469292, 2025). "Furthermore, we discovered that 1,25(OH)2D treatment increased the expression of tumor necrosis factor alpha-induced protein 3 (TNFAIP3), which is required for the ubiquitination and degradation of EMT transcription factors like SNAIL1/2 and ZEB1 in gastric cancers." (PMID 37228489, 2023).
bladder cancer (9 papers, 2014 to 2025). "In bladder cancer, WATP associated with circ0008399 promotes TNFα-induced protein 3 (TNFAIP3) mRNA stability via an m6A-dependent mechanism, inducing cisplatin resistance." (PMID 39806412, 2025). "The circ0008399/WTAP/TNFAIP3 pathway can help increase cisplatin treatment sensitivity in bladder cancer." (PMID 36203569, 2022). "Circ0008399 interacts with WTAP in bladder cancer to increase the stability of TNFAIP3 mRNA in an m6A-dependent manner, thereby inducing tumor cell resistance to cisplatin." (PMID 36139062, 2022). "Tumor suppressor and other cancer-associated genes were also identified, including TNFAIP3, SGK1, and PSCA, which have been implicated in MM or bladder cancer." (PMID 24466111, 2014). "circ0008399/WTAP promotes TNFAIP3 expression by increasing m6A-dependent TNF alpha induced protein 3 (TNFAIP3) mRNA stability in bladder cancer cells, which in turn inhibits bladder cancer cell apoptosis and mediates reduced bladder cancer chemosensitivity to cisplatin." (PMID 36139062, 2022). "In bladder cancer, circ0008399 interacts with WTAP to facilitate the formation of MTC, stabilizing TNF alpha-induced protein 3 (TNFAIP3) mRNA by elevating its m6A modification level, which reduces the chemosensitivity to cisplatin." (PMID 36810281, 2023). "In bladder cancer, WTAP can also modulate cisplatin sensitivity by enhancing the expression of TNF Alpha Induced Protein 3 (TNFAIP3)." (PMID 37297015, 2023). "By increasing the expression of TNFAIP3, the Circ0008399/WTAP combination can prevent bladder cancer cells from dying." (PMID 36203569, 2022).
glioma (8 papers, 2009 to 2025). A benign or malignant brain and spinal cord tumor that arises from glial cells (astrocytes, oligodendrocytes, ependymal cells). "In four RNA‐seq cohorts of glioma, the correlation between the IGLoS signature and the expression of 74 key immune modulators showed an overwhelmingly positive correlation, with TNFAIP3 and TRAF3IP3 showing the most significant association with immune modulators." (PMID 40714831, 2025). "The IGLoS signature consists of six immune infiltration‐related genes associated with the survival of diffuse patients with glioma, which are CCL19, ICOSLG, IL11, PTGES, TNFAIP3, and TRAF3IP3." (PMID 40714831, 2025). "TNFAIP3 regulates glioma stem cell survival, increases resistance to alkylating agents, and is considered a poor prognostic marker in GBM." (PMID 37892185, 2023). "Immunohistochemical staining revealed that five genes (ZEB1, CA9, HSPb1, STAT3, and TNFAIP3) had a higher expression in glioma tissues than in normal tissues." (PMID 35711838, 2022). "Moreover, ZEB1, CA9, HSPB1, STAT3 and TNFAIP3 of the overlapping genes were upregulated in glioma tissues." (PMID 35711838, 2022). "And experiments in vitro showed that GALM could promote the epithelial-to-mesenchymal transition (EMT) process of glioma cells and could be regulated by TNFAIP3 in glioma cells." (PMID 35127693, 2021). "Notably, the expression of GALM increased significantly after overexpression of TNFAIP3 in the glioma cell." (PMID 35127693, 2021). "Therefore, we proposed that highly expressed GALM maintained by TNFAIP3 could promote the malignancy of glioma by regulating the EMT process." (PMID 35127693, 2021). "Next, we used the LASSO regression to further select six key regulators consisting of CCL19, ICOSLG, IL11, PTGES, TNFAIP3, and TRAF3IP3, and they were named the Immune Glioma Survival Signature (IGLoS signature)." (PMID 40714831, 2025). "In the Gusu in‐house dataset consisting of 24 patients with glioma, TRAF3IP3, TNFAIP3, ICOSLG, IL11, and PTGES, showed a trend of increasing expression with increasing tumor grade, whereas CCL19 was not." (PMID 40714831, 2025). "For instance, OTUB1 in glioma, CRC, GC, and HCC; OTUB2 in BC; OTUD2 in NSCLC; TNFAIP3 in BC and ESCC." (PMID 40469292, 2025). "The hypoxia regulation of several new genes comprised in this cluster including ZNF395, TNFAIP3, and TREM1 was experimentally confirmed in glioma cell lines and primary monocytes exposed to hypoxia in vitro." (PMID 19536297, 2009). "By analyzing the expression levels of DUBs and their correlation with GALM in gliomas, combined with in vitro experiments, four DUBs were selected, namely, USP18, TNFAIP3, USP39, and USP38." (PMID 35127693, 2021).
hepatocellular carcinoma (8 papers, 2013 to 2025). A malignant tumor that arises from hepatocytes. "Another NF-κB inhibitor, TNFAIP3, is targeted by miR-29c in hepatocellular carcinoma cells and by miR-125a and miR-125b in DLBCL." (PMID 38539461, 2024). "Overexpression of miRNA-29c in hepatitis B virus-related hepatocellular carcinoma cells effectively suppressed TNFAIP3 expression and HBV DNA replication, as well as inhibiting cell proliferation and inducing apoptosis." (PMID 23840538, 2013). "In addition, in Hepatocellular carcinoma cells (HCC) that were infected with hepatitis B virus (HBV), overexpression of miR-29c effectively suppressed the expression of TNFα-induced protein 3 (TNFAIP3) which plays an essential role in regulating inflammation and immunity." (PMID 31557989, 2016).
melanoma (8 papers, 2006 to 2025). A malignant, usually aggressive tumor composed of atypical, neoplastic melanocytes. "Initially identified as a tumour suppressor gene in CRC, HCC and other cancers, TNFAIP3 was later shown to promote tumour cell growth and dissemination in BC, GC, melanoma and various other malignancies." (PMID 39724264, 2025). "In melanoma, the orchestrated deletion of TNFAIP3 significantly diminishes melanoma cell proliferation and tumour growth in mouse models." (PMID 39724264, 2025). "TNFAIP3 has been identified as a druggable target for melanoma in mice and in inflammatory lung disease." (PMID 37892185, 2023). "In the B16 mouse melanoma tumor model, TNFAIP3 silencing in DCs resulted in an augmented amount of tumor-specific cytotoxic T cells; in AML, TNFAIP3 depletion in AML-DCs potentiated autologous cytolysing T cell (CTL)-specific killing of progenitor AML cells via the NF-κB pathway." (PMID 40469292, 2025). "An typical example is TNFAIP3 mutation indicates low responses to PD-1 inhibitor in NSCLC and cervical cancer patients as showed in the present study, which is also supported by a study on melanoma." (PMID 38951894, 2024). "In a cohort of 54 melanoma patients receiving anti-PD-1 antibody monotherapy, non-responding patients had abundant expressions of immune gene markers such as TNFAIP3 (encoding A20) and TLR3 in tumors, which was associated with a dampened immune response." (PMID 37175874, 2023). "Tumor necrosis factor alpha-induced protein 3 (TNFAIP3), also known as A20, was a ubiquitin-editing enzyme that promotes melanoma cell proliferation in vitro and melanoma growth in vivo through the overexpression of cyclin D and phosphor Rb30." (PMID 33436536, 2021).
nasopharyngeal carcinoma (8 papers, 2016 to 2025). A carcinoma arising from the nasopharyngeal epithelium. "In contrast, other OTU members exert anti-cancer effects in specific cancers, such as YOD1 in HNSCC and cervical cancer; OTUD1 and OTUD6B in clear cell renal cell carcinoma (ccRCC); TNFAIP3 in nasopharyngeal carcinoma (NPC)." (PMID 40469292, 2025). "Overall, miR-19b-3p regulated nasopharyngeal carcinoma radioresistance by targeting TNFAIP3." (PMID 27919278, 2016). "For nasopharyngeal carcinoma (NPC), radiotherapy is the primary treatment strategy, but significantly upregulated miR-19b-3p decreases NPC radiosensitivity by targeting TNFAIP3 to increase NF-κB activity." (PMID 29616037, 2018).
psoriatic arthritis (8 papers, 2013 to 2025). Joint inflammation associated with psoriasis. "On the other hand, polymorphisms in IL23R, TNFAIP3, PTPN22 (tyrosine-protein phosphatase non-receptor type 22), IL12B, RUNX1 (CD8-lymphocyte activation and differentiation), IL13, KIR (killer-cell immunoglobulin-like receptor), and MAGI1 genes have shown association with psoriatic arthritis." (PMID 37628670, 2023).
diffuse large B-cell lymphoma (7 papers, 2010 to 2025). "The deletions or mutations of TNFAIP3 are found in about 30% of patients with diffuse large B-cell lymphoma, while reinforced TNFAIP3 induces apoptosis and cell growth arrest 34, suggesting TNFAIP3 is a tumor suppressor." (PMID 33456565, 2021). "EV-mediated transfer of miRNAs between diffuse large B-cell lymphoma (DLBCL) cells, such as miR-125b-5p targeting TNFAIP3, has specifically been demonstrated to reduce sensitivity to rituximab; however, the mechanism is unclear." (PMID 41551601, 2025). "For example, in diffuse large B-cell lymphoma (DLBCL), constitutive activation of the NF-κB signaling pathway occurs through the suppressive effect of TNFAIP3 which normally inhibits the activation of this pathway by miR-125b." (PMID 34199293, 2021).
glioblastoma (7 papers, 2009 to 2026). The most malignant astrocytic tumor (WHO grade IV). "Inhibition of TNFAIP3 compromisesgrowth and survival of glioblastoma stem cells via inhibition ofcell cycle progression and NF-κB activity, and increases survival of micebearing glioblastome xenografts." (PMID 21637860, 2011). "In contrast, ZNF395 and KISS1R expression and their hypoxia induction were observed in all four glioblastoma cell-lines, while TNFAIP3 was hypoxia-inducible in LN229 and LNZ308." (PMID 19536297, 2009). "TNF alpha induced protein 3 (TNFAIP3, A20) is a tumor enhancer in glioma and inhibits apoptosis in glioblastoma." (PMID 27344170, 2016). "Down‐regulation of EPHB3 and TNFAIP3 activated the PI3K/Akt and NF‐κB signaling pathway, enhanced proliferation and inhibited apoptosis of glioblastoma cells, and eventually enhanced the TMZ resistance in glioblastoma." (PMID 35582627, 2022). "Our analysis of expression profiles from four independent glioblastoma datasets suggests that hypoxia may induce TREM1, TNFAIP3 and BIRC3 in the inflammatory compartment." (PMID 19536297, 2009). "Conversely, 10 cancer types, such as esophageal cancer (ESCA), glioblastoma multiforme (GBM), and adrenocortical carcinoma (ACC), exhibited significant TNFAIP3 upregulation (p < 0.05 for all comparisons)." (PMID 41461391, 2026). "To determine whether deregulation of negative regulators of NF-κB has a role in constitutive NF-κB activation in glioblastoma, we analyzed expressions of the NF-κB regulators NFKBIA, TNFAIP3, TNIP1 and TNIP2 in glioblastoma patients from The Cancer Genome Atlas (TCGA)." (PMID 28166199, 2017).
Hodgkins lymphoma (7 papers, 2013 to 2025). A heterogeneous group of malignant lymphoid neoplasms of B-cell origin characterized histologically by the presence of Hodgkin and Reed-Sternberg (HRS) cells in the vast majority of cases. "Notably, SBS25 has been linked to Hodgkin lymphoma and TNFAIP3 mutations." (PMID 40780199, 2025). "A negative regulator of the nuclear factor (NF)-κB pathway, A20 (TNFAIP3), is inactivated in several types of lymphomas; particularly in diffuse large B-cell lymphoma (DLBCL), classical Hodgkin's lymphoma, and extranodal marginal zone lymphoma of the mucosa-associated lymphoid tissue." (PMID 23418597, 2013).
myeloma (7 papers, 2014 to 2023). "Also, TNFAIP3 was upregulated in a multiple myeloma cell line after treatment with realgar, an arsenic sulfide mineral." (PMID 27838757, 2017). "Deletions of NFκB-pathway modulating genes TNFAIP3, BIRC2/BIRC3, TRAF3 or CYLD were identified in 16.6, 4.8, 13.9 and 16.9% of Myeloma XI cases, respectively." (PMID 28584253, 2018). "Regardless of the mechanism, NGS findings suggest a clonal relationship with clonal evolution and a possible role of NF1, TNFAIP3 and TRAF3 in myeloid transformation of plasma cell myeloma." (PMID 29463311, 2018). "MMCLs were treated with different concentrations of inhibitors or control compound for 16 h, and then NFkB activity was measured by determining the RNA expression levels of 3 NFkB target genes - cIAP2, TNFAIP3, NFKB2, which are the most sensitive target genes in myeloma cells." (PMID 24980832, 2014).
breast tumors (6 papers, 2012 to 2023). "Breast tumors presenting high expression of CD274 upregulated some ferroptosis drivers associated with prognosis: IDO1, IFNG and TNFAIP3." (PMID 38201582, 2023). "Down-regulation of CXCL14 and TNFAIP3 has been described in various primary tumor entities including breast tumors, but to our knowledge, their role in metastasis has not been reported." (PMID 24833255, 2014). "In breast tumors from the TCGA cohort, the expression of CD274 is associated with overall survival, and tumors presenting high expression levels of CD274 upregulated some ferroptosis-driver genes also associated with prognosis, like IDO1, IFNG and TNFAIP3." (PMID 38201582, 2023). "The expression of CD274, IFNG, TNFAIP3 and IDO1 was investigated in an independent cohort of the transcriptome: METABRIC cohort comprising 1866 breast tumors." (PMID 38201582, 2023). "To investigate the role of TNFAIP3 in FGFR1-promoted breast tumor growth in vivo, we injected DCIS-iFGFR1 #2 parent control cells and TNFAIP3 KO DCIS-iFGFR1 cells into the fat pads of nude mouse mammary glands." (PMID 30111373, 2018). "Several genes associated with myeloid derived suppressor cells (MDSC) activity (including TNFAIP3 and XCL2), were also observed to be upregulated in both the breast tumor and the placenta tissue." (PMID 27852037, 2016). "Modulation of genes related with invasion, metastasis and chemoresistance (ICAM-1, CXCL1, TNFAIP3, IL8) were confirmed in additional doxorubicin-treated cell lines and fresh primary human breast tumors." (PMID 24344116, 2014). "In the breast tumor transcriptome from the TCGA cohort, univariate overall survival analyses according to the expression of ferroptosis drivers highlighted a significant favorable expression for three of them: IFNG, IDO1 and TNFAIP3 conjointly with CD274 expression (univariate Cox p-value = 0.08)." (PMID 38201582, 2023). "Furthermore, high TNFAIP3 expression levels were observed in more aggressive breast tumours (ERα/PR negative and high histological grade)." (PMID 23144930, 2012).
coronary artery disease (6 papers, 2009 to 2023). "It is also of interest that a TNFAIP3 SNP with strong correlation (r2 > 0.9) with the rs582757 SNP is associated with reduced expression of TNFAIP3 and with coronary artery disease in patients with type 2 diabetes." (PMID 19292917, 2009).
lupus nephritis (6 papers, 2015 to 2024). Glomerulonephritis in the context of systemic lupus erythematosus. "Three novel TNFAIP3 mutations have been reported as causes of lupus nephritis, adding TNFAIP3 mutations to the list of causes of Mendelian lupus nephritis." (PMID 38772735, 2024). "The TNF-α inhibitor etanercept and the IL-1 receptor antagonist anakinra markedly suppress NF-κB activation and have been successfully used in patients with lupus nephritis caused by TNFAIP3 mutations." (PMID 38772735, 2024). "TNFAIP3 mutations, such as Asp212Glyfs38 (c.634+2T>C), exon 7–8 deletion, or p.Ala434Ter (c.1300_1301delinsTA), were associated with lupus nephritis." (PMID 39125844, 2024). "TNFAIP3 mutations were observed in lupus and lupus-like phenotypes, such as systematic lupus erythematosus (SLE) and lupus nephritis." (PMID 39125844, 2024). "Kidney tissue samples from lupus nephritis patients were shown to exhibit elevated let-7a, -7e, -7i, and 7j miRNA levels and decreased TNFAIP3/A20 protein levels compared to controls." (PMID 33348917, 2020). "Consistently, the genes encoding two NF-κB-negative regulators, A20 (also called TNFAIP3) and A20-binding inhibitor of NF-κB1 (ABIN1; also called TNIP1), have been associated with human lupus and lupus nephritis." (PMID 26579219, 2015). "Although there exists evidence indicating that microRNAs (miRNAs) modulate the expression of TNFAIP3, whether and how miRNAs regulate TNFAIP3 and contribute to lupus nephritis (LN) is still not well understood." (PMID 26110642, 2015).